STAT3 (signal transducer and activator of transcription 3)
Diseases named in the same sentence as STAT3 in open-access papers (continued):
Sharing a sentence is not in itself a finding about the gene and the disease.
ovarian carcinoma (continued). "A recent study showed that blockade of lncRNA PVT1 reduced the expression of PD-L1 through the JAK2/STAT3 pathway, thereby inhibiting cell proliferation and invasion in cisplatin resistant epithelial ovarian cancer." (PMID 37936074, 2023). "A study based on ovarian cancer was made to evaluate the effects of kaempferol on the Mitogen-activated protein kinase (MEK) MEK/extracellular signal-regulated kinases (ERK) as well as STAT3 signaling pathway of ovarian cancer cells." (PMID 37239974, 2023). "As expected, GEPIA database analysis revealed that there was a positive correlation between GANAB and STAT3 expression in ovarian cancer." (PMID 37781028, 2023). "The inhibitor of DNA binding 1 (ID1), significantly increased in our platinum-resistant PDOs, has been described to induce autophagy and chemoresistance through the STAT3/ATF6-mediated signalling pathway in ovarian cancer." (PMID 37686015, 2023). "STAT3 is hyperactive in ovarian cancer, and increased p-STAT3 levels are mediated by increased reactive oxygen species production in hypoxic cancer cells." (PMID 37575547, 2023). "In conclusion, CHAF1A promotes the proliferation and growth of epithelial ovarian cancer cells by affecting the phosphorylation of JAK2/STAT3 signaling pathway." (PMID 37575547, 2023). "Immunohistochemistry and protein analyses of STAT3 in ovarian cancer showed that the level of STAT3 significantly increased in ovarian cancer tissues and cell lines." (PMID 38067351, 2023). "The JAK/STAT3 pathway is often upregulated in ovarian cancer, leading to an immunosuppressive tumor microenvironment that can promote tumor cell growth and survival, inhibits apoptosis, and enhances angiogenesis and immune evasion." (PMID 38038814, 2023). "Studies have shown that the expression of STAT3 is up-regulated in ovarian cancer tissues, and the resistance of ovarian cancer cells to cisplatin is reduced through PI3K/AKT pathway." (PMID 36793374, 2023). "STAT3 is raised and the resistance of ovarian cancer cells to cisplatin is reduced by PI3K/AKT pathway." (PMID 36793374, 2023). "Treatment of olaparib-resistant ovarian cancer cell line with napabucasin, the STAT3 inhibitor, improved PARPi sensitivity." (PMID 37448521, 2023). "Treatment of olaparib-resistant ovarian cancer cell line with napabucasin, the STAT3 inhibitor, down-regulated the STAT3 downstream genes, disturbed tumor progression, and improved PARPi sensitivity." (PMID 38248100, 2023). "We found that butein increased the expression of p27kip1 by regulating the mechanism of STAT3 and FoxO3a in ovarian cancer." (PMID 37047012, 2023). "Recently, we have confirmed the formation of IL-6/STAT3/HIF-1α autocrine signaling loop in ovarian cancer cells in vitro and in vivo, which confers chemoresistance against cisplatin to ovarian cancer." (PMID 36814597, 2023). "The treatment of SKOV3 and OVCAR3 ovarian cancer cells with the STAT3 ODN-decoy led to decreased invasive cancer potential and increased cell sensitivity to paclitaxel." (PMID 38067351, 2023). "In summary, their research reveals overexpression of STAT3 increases ovarian cancer colony formation, proliferation, and resistance to paclitaxel by increasing G6PD expression and pentose–phosphate metabolism flux." (PMID 36902166, 2023). "A recent study investigated the mechanism that mediates the crosstalk between NOTCH and STAT3 pathways in platinum-resistant ovarian cancer and found that STAT3 and JAG1 are overexpressed in such cancer tissues." (PMID 37781534, 2023). "Numerous studies analysing molecular mechanisms of platinum resistance in ovarian cancer have reported that the over-expression of IL-6 is one of the contributing factors for chemo-resistance and poor prognosis via STAT3-mediated activation." (PMID 36765633, 2023). "The Dickkopf-1 WNT signaling pathway inhibitor 1 (DKK1) was upregulated by the inhibition of miR-92a-1 in these STAT3-silenced ovarian cancer cells." (PMID 38067351, 2023).
ovarian carcinoma (continued). "Cisplatin-resistant C13K and SKOV3 ovarian cancer cell lines treated with STAT3 siRNA and cisplatin have an increased ratio of dead cells compared to cells receiving cisplatin alone." (PMID 38067351, 2023). "In ovarian carcinoma-bearing mice, curcumin treatment was shown to suppress pathways mediated by NF-κBand phosphorylated STAT3." (PMID 37376060, 2023). "Studies from our and other laboratories have shown that activation of STAT3 in response to chemotherapy treatment as pre-requisite for cancer stemness and related therapy-resistance in ovarian cancer cells." (PMID 36585738, 2022). "The well-known oncoprotein of STAT3 (signal transducer and activator of transcription 3) is downregulated by miR‐3666, resulting in the retention of ovarian carcinoma progression." (PMID 36578556, 2022). "Platinum-agents have demonstrated increased IL-6 and PGE2 production in ovarian cancer cell lines, with subsequent activation of STAT3 pathway and induction of M2 polarization with upregulation of IL-10." (PMID 35565348, 2022). "A pluripotent stem cell marker, Nanog, is associated with the STAT3 molecule to activate therapy resistance genes ABCB1 and MDR1 in breast and ovarian cancer cells." (PMID 36550571, 2022). "For example, triptolide contributes to autophagy through reactive oxygen species generation in ovarian cancer SKOV3/DDP cell lines resistant to cisplatin by inhibiting STAT3 signaling." (PMID 36474621, 2022). "IL-6 inhibitors also impacted the STAT3 signaling by reducing STAT3 phosphorylation and the expression of STAT3 downstream anti-apoptotic genes in ovarian cancer." (PMID 36246629, 2022). "A study showed that up-regulated ALDH1A2 suppressed ovarian cancer cell proliferation via activation of transcription 3 (STAT3)." (PMID 36287961, 2022). "Numerous studies have connected STAT3 constitutive activation to chemoresistance in ovarian cancer cells." (PMID 36364232, 2022). "Gal-3 can also induce phosphorylation in the signal transducer and activator of transcription 3 (STAT-3) in ovarian cancer cell spheroids." (PMID 35204790, 2022). "Frequent somatic mutations in the 3′-UTR of GAPDH have been reported to promote the growth of ovarian cancer by sponging miR-125 and thereby affecting the expression of Signal Transducer and Activator of Transcription 3 (STAT3)." (PMID 37082114, 2022). "It has been previously reported that NF-κB and STAT3 signaling play important roles in progression and development of ovarian cancer." (PMID 35465837, 2022). "IL-8 binds CXCR1 on ovarian cancer cells and promotes metastasis through activation of STAT3 and p38 MAPK pathways." (PMID 35574025, 2022). "Anti-OSMR antibody inhibited the growth of ovarian cancer cells in vitro and in vivo by suppressing STAT3 activation." (PMID 35565185, 2022). "Here, the authors found that TRIM47 knockdown reduced STAT3 phosphorylation at Tyr705 in both cultured and xenografted ovarian cancer cells, followed by reduced expression of the STAT3 target genes MCL-1, MMP2, and c-MYC." (PMID 36288633, 2022). "The injection of exogenous Gal-3 resulted in increased STAT3 phosphorylation (pSTAT3) in ovarian cancer cells." (PMID 36364232, 2022). "For example, miR-141-3p-containing extracellular vesicles from epithelial ovarian cancer cells promote vascular endothelial cell generation by activating the JAK/STAT3 signaling pathway and inducing VEGFR2 expression." (PMID 36439168, 2022). "The targeted inhibition of the JAK1/STAT3 pathway can effectively prevent the progression and metastasis of ovarian cancer." (PMID 35991559, 2022). "The reduced antitumor effects of Olaparib in ovarian cancer cells can be attributed partially to the induction of STAT3 phosphorylation through decreasing PolyADP-ribosylation (PARylation)." (PMID 36324587, 2022).
ovarian carcinoma (continued). "A recent study showed that β-Ele combined with paclitaxel inhibited growth and induced apoptosis of ovarian cancer cells, suggesting that β-Ele enhanced the anti-ovarian cancer effects of paclitaxel through regulation of the STAT3/NF-κB signaling pathway." (PMID 35909161, 2022). "In the case of recurrent ovarian carcinoma, tocilizumab decreased STAT3 activation/phosphorylation in patient immune cells (e.g., myeloid cells, CD4+ T and CD8+ T only at a high dose), most probably due to the suppression of IL-6R signalling." (PMID 36429126, 2022). "Overexpression of STAT3 in hypoxic condition is crucial for exosome release and triggering cisplatin resistance in ovarian cancer." (PMID 35765040, 2022). "Tumor growth and resistance to cisplatin were promoted via ALKBH5-HOXA10 loop through mediating JAK2/STAT3 signaling pathway in epithelial ovarian cancer." (PMID 36545327, 2022). "For instance, signal transducer and activator of transcription 3 (STAT3) promotes exosome release by down-regulating Rab7 and up-regulating Rab27a in ovarian cancer cells under hypoxia conditions." (PMID 35812406, 2022). "Signal transducers such as STAT3 in various cancer classifications, including ovarian cancer, are aberrantly activated by tyrosine phosphorylation." (PMID 36288633, 2022). "Other reports have illustrated that RHPN2 activates the STAT3 pathway and expedites the progression of ovarian cancer, and the use of the STAT3 inhibitors signally eases the malignant cell behaviors induced by RHPN2." (PMID 35475457, 2022). "In ovarian cancer, the signal transducer and activator of transcription 3 (STAT3), an ER stress inducer, is activated through ATF6." (PMID 36497032, 2022). "Saini and co-workers observed that activated STAT3 is highly expressed in ascites-derived ovarian cancer cells (ADOCC)." (PMID 36429126, 2022). "Activated STAT3 has been shown to increase the proliferation, metastasis, and chemoresistance of ovarian cancer cells, as well as angiogenesis." (PMID 36288633, 2022). "Immunoblotting analysis revealed that APG-2449 downregulated Y397-FAK autophosphorylation (p-FAK) and downstream signaling factors p-AKT, p-ERK1/2, and p-STAT3 in PA-1 ovarian cancer cells." (PMID 35820889, 2022). "Previous studies have reported that ADSCs can promote tumor progression and ovarian cancer metastasis by regulating several regulatory factors, such as MMPs, STAT3, and TMSB4X." (PMID 36359787, 2022). "Clinical trials have been conducted with STAT3 inhibitors for the treatment of cholangiocarcinoma, breast and ovarian cancers." (PMID 36248966, 2022). "Further, it inhibited STAT3, resulting in the downregulation of the BCL-2 gene downstream of STAT3, and improved the antitumor effect of cisplatin in a mouse xenograft model for ovarian cancer." (PMID 35883021, 2022). "It is well documented that chemotherapy-induced ROS and oxidative stress can regulate STAT3 transcriptional activity in ovarian cancer cells, creating another layer of complexity in the comparative responses of gRNA1 and gRNA2 cells to PTX." (PMID 36585738, 2022). "Previous study demonstrated that overexpression of FBP1 conferred sensitivity to cisplatin via modulating STAT3 in ovarian cancer." (PMID 36358906, 2022). "The authors also used GEPIA to analyze the mRNA levels of TRIM47 and STAT3 target genes in ovarian cancer tissues." (PMID 36288633, 2022). "Additional co-culture experiments of ovarian cancer cells with macrophages demonstrate induced cellular stemness via IL-8/STAT3 signaling." (PMID 35565348, 2022). "Knockdown of lncRNA PVT1 repressed tumor progression via targeting JAK2/STAT3/PD-L1 in cisplatin-resistant ovarian cancer cells." (PMID 36105363, 2022). "Cardamonin and alpinetin can suppress proliferation and induce apoptosis of prostate and ovarian cancer cells by modulating the STAT3 pathway." (PMID 36106139, 2022).
ovarian carcinoma (continued). "The STAT3-miRNA-92-Wnt signaling pathway was beneficial for ovarian cancer spheroids formation and generation of cancer stem-like cells." (PMID 35541892, 2022). "CCL11 is a cytokine that induces MEK-1, ERK1/2, and STAT3 phosphoproteins as a mechanism for conferring anti-apoptotic and cisplatin-resistance potential in ovarian carcinoma." (PMID 36528667, 2022). "RHPN2, a RhoA-binding protein, promotes malignant cell proliferation in ovarian cancer by activating the JAK2/STAT3 signaling pathway." (PMID 35893033, 2022). "It was demonstrated that miR-29a-3p and miR-21-5p synergistically inhibit STAT3, regulate Treg/Th17 cells and induce an imbalance, creating an immunosuppressive microenvironment that promotes ovarian cancer progression and metastasis." (PMID 36439168, 2022). "The results demonstrated that compared with stage III-IV ovarian cancer patients, stage I–II ovarian cancer patients had significantly lower STAT3/p-STAT3 expression levels (OR = 0.36, 95% CI = 0.22–0.59, p < 0.00001)." (PMID 34789292, 2021). "IL-27 also reduced the proliferation of human ovarian cancer cells by activating STAT3 and inhibiting Akt signaling pathways." (PMID 33418929, 2021). "Similar findings were also observed in p-STAT3 and total STAT3 in ovarian cancer tissues compared to benign and normal tissues." (PMID 34358244, 2021). "S-nitroso-N-acetylpenicillamine (SNAP), an NO donor, can rescue the inhibition of STAT3 phosphorylation induced by a certain antitumor drug to prevent apoptosis of human ovarian cancer OVCAR3 and SKOV3 cells at low concentration." (PMID 34356634, 2021). "Multiomics profiling reveals STAT3 regulated several biological processes in ovarian cancer, including epithelial–mesenchymal transition, cell cycle progression, and E2F signaling." (PMID 34539736, 2021). "Our findings show that STAT3 expression has potential as a specific biomarker in patients with ovarian cancer, and its increased expression indicates poor patient prognosis." (PMID 34789292, 2021). "STAT3/p-STAT3 expression in ovarian carcinoma versus benign ovarian tumours was compared; the data were from 451 ovarian cancer cases and 164 patients suffering from benign ovarian tumours." (PMID 34789292, 2021). "We decided to choose ERK 1/2, AKT and STAT3, since their expression and activity are usually enhanced in ovarian cancer." (PMID 33478150, 2021). "Our previous studies have shown activation of Stat3 is critical for the development of chemoresistance in ovarian cancer cells." (PMID 35047406, 2021). "Previous studies have shown total STAT3 and phosphorylated STAT3 (p-STAT3) are overexpressed in a subset of chemoresistant ovarian cancer cell lines as compared to their expression in the corresponding chemo-sensitive cell lines." (PMID 33809542, 2021). "C-MYC was expressed at high levels in 45.1% (169/375) of ovarian cancer tissues, 66 (14.9%) patients showed “high” expression of STAT3, and 67 (15.1%) patients showed “high” expression of p-STAT3." (PMID 34363022, 2021). "PT reduced proliferation and migration in ovarian cancer cells by the inhibition of the STAT3 pathway." (PMID 33801098, 2021). "We obtained consistent outcomes in the ovarian cancer biomarker subgroups (STAT3 and p-STAT3) (STAT3: OR = 8.53, 95% CI = 5.15–14.13, p < 0.00001; p-STAT3: OR = 11.06, 95% CI = 4.26–28.76, p < 0.00001)." (PMID 34789292, 2021). "This meta-analysis comprised ovarian cancer and borderline ovarian tumour STAT3/p-STAT3 expression data from 4 studies." (PMID 34789292, 2021). "The STAT3 signaling pathway is related to ovarian cancer cell proliferation, metastasis, apoptosis, and differentiation." (PMID 34231329, 2021). "The persistent activation of STAT3 signaling have been reported to confer resistance to paclitaxel and cisplatin in cancer cells including ovarian cancer cells." (PMID 33909625, 2021).
ovarian carcinoma (continued). "In fibroblasts senesced upon exposure to PCT, the activation of STAT3 was linked with hypersecretion of IL-6, i.e., one of the agents whose mRNA and protein were upregulated in DIPS ovarian cancer cells." (PMID 34674640, 2021). "To validate a potentially critical role of increasing STAT3 phosphorylation in limiting PARPi therapy efficacy, we tested the effects of Olaparib in multiple human ovarian cancer cell lines." (PMID 34956861, 2021). "In animal models, targeting STAT3 in combination with paclitaxel can synergistically reduce intraperitoneal dissemination and prolong the survival of mice with ovarian cancer." (PMID 34512721, 2021). "Activation of the JAK/STAT3 signaling pathway contributes to the uncontrolled proliferation of cancer cells, including ovarian cancer." (PMID 34330232, 2021). "Pharmacologic inhibition of PARP1 with PARPi enhanced the tyrosine 705 (Y705) phosphorylation of STAT3 (p-STAT3) in ovarian cancer cell lines, which was mediated by dePARylation." (PMID 34956861, 2021). "Data of STAT3/p-STAT3 expression in ovarian carcinoma and normal ovary tissue from 3 studies (4 trials) were included in this meta-analysis to compare STAT3/p-STAT3 expression in ovarian carcinoma versus normal ovarian tissue." (PMID 34789292, 2021). "Inhibition of the JAK/STAT3 signal suppresses the growth of ovarian cancer cells and reduces their dissemination to the peritoneal cavity." (PMID 34330232, 2021). "Activation of the IGF1R/STAT3 signaling axis contributes to enhanced invasion and migration in ovarian cancer." (PMID 34185427, 2021). "The IL-6/JAK2/STAT3 pathway has been shown to increase proliferation and migration of ovarian cancer cells, and ovarian cancer patient derived ascites cells, as well as the migration and invasion of breast cancer cells." (PMID 34912237, 2021). "Our results demonstrate the regulatory function of C-MYC/FBP1/STAT3 signaling axis on cell proliferation, metastasis, and chemoresistance in ovarian cancer." (PMID 34363022, 2021). "Previously, high levels of activated STAT3 have been found to correlate with advanced-stage ovarian cancer and poor prognosis." (PMID 34956861, 2021). "Since both siRNA-mediated and pharmacological STAT3 inhibition has been previously shown to reverse paclitaxel and cisplatin resistance in ovarian cancer cells, we tested the reliance of Olaparib-resistant ovarian cancer cells on STAT3 signaling for survival." (PMID 34956861, 2021). "It is necessary to assess larger ovarian cancer patient cohorts to confirm the central role of STAT3 in promoting ovarian cancer progression after PARPi treatment." (PMID 34956861, 2021). "However, it remains unknown whether PARPi treatment activate STAT3 in ovarian cancer patient tumors to promote therapy resistance, and whether PARPi impact STAT3 activity in tumor-associated immune cells to suppress their ability to mount antitumor immune responses." (PMID 34956861, 2021). "We obtained consistent outcomes in the ovarian cancer biomarker subgroups (STAT3 and p-STAT3) (STAT3: OR = 0.37, 95% CI = 0.20–0.69, p = 0.002; p-STAT3: OR = 0.65, 95% CI = 0.44–0.97, p = 0.035)." (PMID 34789292, 2021). "Comparison of ovarian cancer patient-matched tumor biopsies before and after PARPi therapy revealed that STAT3 activity was significantly higher in tumor cells and tumor-associated immune cells and fibroblasts post PARPi treatment." (PMID 34956861, 2021). "We obtained consistent outcomes in the ovarian cancer biomarker subgroups (STAT3 and p-STAT3) (STAT3: OR = 4.11, 95% CI = 2.43–6.96, p < 0.00001; p-STAT3: OR = 2.88, 95% CI = 1.81–4.60, p < 0.00001)." (PMID 34789292, 2021). "The present meta-analysis indicated that high STAT3/p-STAT3 expression is likely predictive of an unfavourable prognosis in ovarian cancer patients." (PMID 34789292, 2021).